CDK2 (cyclin dependent kinase 2)
Diseases named in the same sentence as CDK2 in open-access papers (continued):
Sharing a sentence is not in itself a finding about the gene and the disease.
tumor (continued). "Whilst NU-6102 showed no activity (IC50 > 10 μM), probably due to its higher sensitivity towards CDK1, AUZ 454 exhibited considerable levels of anti-tumour activity in the range of μM, suggesting an abnormal behaviour of CDK2 in HGSC." (PMID 37120667, 2023). "TOPBP1 interacting checkpoint and replication regulator (TICRR), a hub gene of the Cdk2-mediated initiation step of DNA replication, has been shown an essential role in tumorigenesis by accelerating the DNA replication of tumor cells." (PMID 38152367, 2023). "By sustaining EGFR/CDK2 activity and by being expressed at such high levels in this tumor entity, EMP3 provides an additional level of resistance that protects tumor cells from targeted kinase inhibitors." (PMID 37936247, 2023). "IHC results showed that the combination decreased the expression of Ki67, CDK2, and p-STAT3 expression in tumor tissues, while Pal alone showed elevated CDK2 expression and upregulated p-STAT3 expression." (PMID 37752122, 2023). "Overexpression of CDK2 leads to abnormal regulation of the cell cycle, which is directly related to the overproliferation of tumor cells." (PMID 36969029, 2023). "CDK2 is a central factor in the oncogenic signaling pathway and has an important role in the tumor process." (PMID 36874006, 2023). "CDKN1A functions as a tumor suppressor by blocking cell cycle progression via inhibiting CDK1 and CDK2, and CDKN1A-deficiency promotes spontaneous and induced tumors in different tissues." (PMID 36765862, 2023). "Gli-related genes, including CDKN2A/p16/INK4A, Myc, and CDK2, by promoting androgen-independent tumor cell growth, lead to biochemical and tumor recurrence and lead to tumor recurrence." (PMID 37175453, 2023). "Other authors have also shown that BRCA1 promotes cell cycle arrest and tumor growth suppression through the induction of the cyclin-dependent kinase 2 (CDK2) inhibitor p21." (PMID 37444415, 2023). "The analysis revealed that the expression levels of RXRB and CDK2 were higher in lower pathological stages of the tumor." (PMID 37509183, 2023). "Our study found six genes (PCNA, CDC6, CDC7, CDT1, CDK2, and RBBP8) that were most significantly linked with expression levels of key genes and tumor progression." (PMID 37656243, 2023). "We further tested the level of tumor-infiltrating lymphocyte (TIL) by CIBERSORT in the TNBC-enriched Guy’s cohort, and we investigated their association with cyclin E and CDK2 expression." (PMID 35884422, 2022). "The SLCO4A1-AS1-induced increase in Cdk2 levels activates the c-Myc signalling pathway by promoting the phosphorylation of c-Myc at Ser62, resulting in increased tumour growth." (PMID 35039060, 2022). "As transcription factors, FOXM1 can regulate downstream cell cycle-related genes, including PLK, cyclin B1, cyclin D1, and Cdk2, to promote cell proliferation and tumor progression." (PMID 36585925, 2022). "For example, circ-Foxo3 can form a Foxo3-p21-CDK2 ternary complex by interacting with cyclin-dependent kinase 2 (CDK2) and p21, resulting in the inhibition of CDK2 function and the blockage of cell cycle progression, thereby regulating tumor development." (PMID 36465346, 2022). "Cyclin-dependent kinase 2 (CDK2) regulates the progression of the cell cycle and is critically associated with tumor growth." (PMID 35592410, 2022). "TNBC samples with a high CCNE1 or CDK2 level were more likely to feature an immune-rich tumor microenvironment (TME) with a significant level of lymphocytic infiltration (moderate to brisk level)." (PMID 35884422, 2022). "The tumor suppressor effect of miR-124 was also observed through the inhibition of cell cycle-related cyclin D1, cyclin-dependent kinase 2 (CDK2), cyclin-dependent kinase 4 (CDK4), and cyclin-dependent kinase 6 (CDK6)." (PMID 35326471, 2022). "Collectively, these data demonstrate that SLCO4A1-AS1 exerts tumour-promoting functions in CRC by activating the Cdk2/c-Myc axis." (PMID 35039060, 2022).
tumor (continued). "The downregulated SKP2 caused accumulation of its substrates, p27 and p21, which further inhibited the activity of the G1 phase-related protein, CDK2, leading to inhibition of cell proliferation and tumor formation." (PMID 33628597, 2021). "It is well known that CCNE1 works by forming a complex with CDK2, and the CCNE1-CDK2 complex is able to pushing cell cycle from G1 to S phase, thereby regulating tumor progression." (PMID 33676555, 2021). "The CDK inhibitor, p27, was first identified as a tumor suppressor protein able to induce G1 phase arrest; it binds to the CDK2/Cyclin E complex and inhibits its activity." (PMID 35127504, 2021). "This complex achieves the tumor-suppressing effect by inhibiting the function of CDK2 and preventing the cell cycle from transitioning from the G1 phase to the G1/S phase, thus having a tumor-suppressing effect." (PMID 34018386, 2021). "For example, latent protein 3C (EBNA3C) of Epstein-Barr virus, the first reported human tumor virus, can directly bind to CDK2, and also cooperate with master transcription factor Bcl6 to regulate the expression of CDK2, thereby promoting cell proliferation." (PMID 33556114, 2021). "We studied the relationship between CDK2 and tumor immunity, providing a new idea for immunotherapy about LUAD." (PMID 34409029, 2021). "Using dinacibil, an approved CDK2 inhibitor, they were able to suppress tumor growth and metastasis in a mouse xenograft model." (PMID 34642317, 2021). "The most important molecules are Cyclin-D1 and CDK2, which are essential proteins for tumor cells to enter the G1 phase to the S phase and to switch from the S phase to the G2 phase." (PMID 34319912, 2021). "Induction of p27kip1 tumor suppressor gene accumulation by attenuating p27kip1 at Thr 187 phosphorylation; inhibition of CDK2 activation through binding with the CDK2 complex; inhibition of mTOR kinase activity by binding with the mTOR complex." (PMID 34630112, 2021). "Immunohistochemistry staining of the tumor tissues also revealed significantly reduced expressions of Rb and CDK2/4/6in vanoxerinedihydrochloride treatment group." (PMID 33579185, 2021). "Treatment of BRCA1 mutant BLBC patient-derived xenograft models with combination PARP and CDK2 inhibition led to tumor regression and increased survival." (PMID 34465787, 2021). "Our study collectively suggested that STAT3/CDK2/4/6 are important onco-immune signatures that contribute to tumor immune invasion, poor prognoses, and immune therapy failure." (PMID 33668805, 2021). "We evaluated the gene expression of miR-525-5p, ARF6, PCNA and CDK2 in the xenograft tumor tissues by RT-qPCR." (PMID 34621682, 2021). "Collectively, our study suggested that STAT3/CDK2/4/6 are important onco-immune signatures that play central roles in tumor immune invasion, poor prognoses and, immune therapy response." (PMID 33668805, 2021). "Immunohistochemistry staining of the tumor tissues showed significantly reduced expressions of Rb, CDK2, CDK4, and CDK6 in vanoxerinedihydrochloride treatment group, as compared to control PBS treatment group." (PMID 33579185, 2021). "Nobiletin downregulated mRNA expression of SKP2 by upregulating the transcription factor, FOXO3A, leading to accumulation of p21 and p27 and the reduction of CDK2, to inhibit cell proliferation and tumor formation." (PMID 33628597, 2021). "In contrast, CDK2 expression was similar in G1 and G2 HCCs but elevated in G3 tumours, pointing towards a role during late-stage hepatocarcinogenesis." (PMID 34830835, 2021).
tumor (continued). "Deficiency of YTHDF1 functionally prevents NSCLC cell proliferation and tumor formation through inhibiting the translational efficiency of cyclin-dependent kinase 2 (CDK2), cyclin-dependent kinase 4 (CDK4), and cyclin D1 (CCND1)." (PMID 34359836, 2021). "The expression levels of cyclin A1 and CDK2 in the tumor tissues of the models were detected with qRT-PCR." (PMID 34992655, 2021). "In vivo experiments showed that co-therapy with CDK2 inhibitor and paclitaxel acted synergistically in tumor suppression of TNBC." (PMID 33541412, 2021). "In particular, the abnormal expression of CDK2 protein is detected in a variety of tumours, which is related to the proliferation of tumour cells." (PMID 33145980, 2020). "We therefore propose that BRAF/MEK/ERK and CDK2 play proapoptotic roles in postmitotic cells while playing pro-proliferative roles in tumor cells." (PMID 33268358, 2020). "We also provide evidence that BRAF/MEK/ERK and CDK2 pathways, while key in tumor cells, play proapoptotic and stress-activating roles in postmitotic cochlear cells, an underappreciated feature of these pathways in postmitotic cells." (PMID 33268358, 2020). "For example, alterations in CDK1 and CDK2 enzyme kinetics parameters will disrupt the regular cell cycle; the in vitro tumor cell proliferation dynamics follows a fractal structure different from normal oscillatory dynamics." (PMID 33297998, 2020). "Local hypoxia in tumors increases VEGF-A signaling, leading to high CyclinE/cdk2 that promotes EC centrosome overduplication, and elevated Plk4 expression occurs in human and mouse tumor vessels." (PMID 32699963, 2020). "We found that BACE2 knockdown led to significantly decreased levels of p‐p65 and key tumour promoters, namely CDK2, CDK4, cyclin D1 and c‐Myc." (PMID 31856384, 2020). "MCF7-PR xenograft mouse models were established to test in vivo tumor growth inhibition with CDK2 siRNA as a single agent and in combination with palbociclib." (PMID 33260316, 2020). "CR8 was shown to target similar Cdks as Roscovitine including Cdk1, Cdk2, Cdk5, Cdk7 and Cdk9, but with much stronger efficacy and a predicted improved anti-tumor potential." (PMID 32380742, 2020). "CDK2 inhibitors that we previously identified in similar screens also showed protection in postmitotic cochlear cells whereas both BRAF inhibitors and CDK2 inhibitors are two known groups of anti-proliferative compounds in tumor cells." (PMID 33268358, 2020). "After LINC00659 inhibition, the protein levels of SUZ12, p21, Cyclin E, Cyclin D and CDK2 in SGC‐7901 tumour tissue were significantly higher than those of SGC‐7901‐LINC00659−/−." (PMID 33145980, 2020). "The copy number analysis of CCA tumor samples indicated a gain in CDK2 (22.8%), CDK5 (14.3%), and CDK9 (5.7%)." (PMID 33116269, 2020). "Significant tumor regression was observed following treatment with CDK2 siRNA when combined with palbociclib compared with palbociclib treatment alone (p = 0.035) or the control siRNA treatment group (p = 0.012)." (PMID 33260316, 2020). "In fact, all of these kinase genes, except CDK2, were significantly highly expressed in tumor tissues." (PMID 31926109, 2020). "PTEN loss results in activation of AKT, CDK1, and CDK2 kinases, which in turn leads to phosphorylation of FOXO1, exclusion of FOXO1 from the nucleus, and loss of the tumor suppressor functions in the nucleus 18, 25-27." (PMID 31410199, 2019). "This positive effect on tumor growth involves activation of c-myc and cyclin E1/CDK2 and their effect on cell cycle distribution." (PMID 30675171, 2019). "This corresponds to the in vitro observation that when CDK2 inhibitor is applied, PD‐L1/L2 in tumor is upregulated as a mechanism of resistance to would be decreased negative immune modulation." (PMID 31657115, 2019). "The western blotting results were consistent with the results of the in vitro experiments; buforin IIb treatment repressed the expression of CDK2 and cyclin A in xenograft tumor tissues." (PMID 31231581, 2019).
tumor (continued). "The effects of buforin IIb on CDK2 and cyclin A in xenograft tumor tissues were analyzed by western blotting and immunohistochemistry." (PMID 31231581, 2019). "Decreased CDK2 activity and the increased presence of p21CIP1 in anti-CDK2 precipitates were consistently observed in multiple tumour cell lines subject to combined MET and CDK4 inhibition." (PMID 31296956, 2019). "p27Kip1 and p21Cip1 are thought to suppress tumor growth and prevent cell cycle progression by inhibiting Cdk2-cyclin E/A kinases." (PMID 31289362, 2019). "In particular, RTK/PI3K-Akt pathway inhibitors and CDK2 inhibitors have been evaluated in combination with CDK4/6 inhibitors very detailed in other tumor entities before." (PMID 31331377, 2019). "Similar to the in vitro results, buforin IIb injection reduced the expression of CDK2 and cyclin A in the tumor tissue." (PMID 31231581, 2019). "The results of the in vivo experiments showed that buforin IIb inhibited tumor growth, and similar to the in vitro findings, the expression levels of CDK2 and cyclin A in the tumor tissue were inhibited by buforin IIb treatment." (PMID 31231581, 2019). "In the present study, the cdk1-cyclin B- and the cdk2-cyclin A-complex were reduced in parental cells treated with temsirolimus, whereas a strong up-regulation was seen in drug resistant tumor cells, particularly when re-treated with temsirolimus." (PMID 31167517, 2019). "Levels of cyclin A, D, and E were analyzed, as well as phosphorylated CDK2 and total CDK2, in tumor lysates that were either cisplatin-sensitive (parental) or cisplatin-resistant." (PMID 31727874, 2019). "Here, we first demonstrated that site-specific phosphorylation of EZH2 by CDK2 is required for tumor cell lineage commitment in tumorigenesis." (PMID 31704972, 2019). "PTEN loss leads to AKT- and CDK1- or CDK2-mediated phosphorylation of FOXO1, exclusion of FOXO1 protein from the nucleus, and loss of its tumor suppressor functions in the nucleus 18, 25-27." (PMID 31410199, 2019). "We presented genetic evidence to demonstrate that CDK2-mediated phosphorylation of EZH2 at T416 is critical for its role as a tumor driver and lineage indicator." (PMID 31704972, 2019). "Our data suggest that not only Palbociclib but also the CDK2-specific inhibitor Milciclib is efficiently inducing apoptosis in tumor lines cultured in serum-free conditions." (PMID 29511348, 2018). "CDKN1A (cyclin-dependent kinase inhibitor 1A; also known as p21, Cip1, Waf1) is a tumor suppressor that regulates cell proliferation and binds to and inhibits kinase activity of Cdk2 and Cdk1, leading to cell cycle arrest." (PMID 30514244, 2018). "To verify the reliability of anti-tumor related targets screened from systems pharmacology, we observe that baicalein treatment, the protein expressions of CDK2 and Bax in H1975 cells were both declined significantly at different dose levels." (PMID 30618763, 2018). "The progression through the G1–S phase—an important step in tumor development—is regulated by changes in the activity of specific CDKs, with CDK2/CDK4-CDK6 controlling the transition from G1 to S phase." (PMID 29502166, 2018). "p27 (also known as KIP1, encoded by CDKN1B) is an atypical tumor suppressor that regulates G0 to S phase transition by binding to and regulating the activity of CDK1 and CDK2." (PMID 30450190, 2018).
tumor (continued). "While specific inhibition of a single CDK is unlikely to be a realistic aim, we have shown that inhibitors with selectivity for CDK2 can effectively limit tumour cell proliferation." (PMID 29222471, 2017). "Mechanistically, overexpression of miR-200b in HCCC cells decreased the expression of cyclin D1 and Cdk2 in order to induce cell cycle arrest and was able restore their expression for the growth of tumor cells." (PMID 29084594, 2017). "Several genomic regions were preferentially amplified or deleted in tumours harbouring IDC, including gain of BCL6 and loss of MTOR, along with gains of a region harbouring CDK2 and ERBB3." (PMID 28067867, 2017). "The activity of cyclin-dependent kinase 2 is important for the G1/S transition, and the retinoblastoma protein is a tumor suppressor whose action is impaired in many tumors." (PMID 28409496, 2017). "We next preformed immunohistochemistry on paraffin embedded mouse xenograft tumor samples with an antibody directed against CDK2." (PMID 29088865, 2017). "We focus on the tumor suppressor p27KIP1, whose cyclin E/CDK2 and cyclin A/CDK2-dependent phosphorylation results in subsequent degradation." (PMID 28056778, 2017). "Knock-down of cdk2 and cyclin A resulted in significant cell growth inhibition in all tumor sublines, compared to the untreated cells and the mock control." (PMID 29299126, 2017). "We concluded that Roniciclib likely inhibits an ESC-like, tumour aggressive signature in HR-NB by inhibiting CDK2." (PMID 28246384, 2017). "The IHC results also confirmed the activation of CHK1/CDC25A/CDK2 pathway in xenograft tumor generated from Mus81‐inhibited HepG2 cells under EPI treatment." (PMID 26714930, 2016). "In summary, these results indicate that the synergistic inhibition of tumor growth by the HF-ATS combination is associated with the increased levels of p21Cip1 and p27Kip1 and the decreased phosphorylation of CDK2." (PMID 27385212, 2016). "OS tumour samples showed an inherent overexpression of CDK2, and high expression levels at diagnosis of this kinase appeared to negatively impact on clinical outcome." (PMID 27898692, 2016). "The CDK2-cyclin E complex was well known as they play an important role in tumor development through regulation of the cell cycle." (PMID 26992224, 2016). "CDK2 is expressed at a higher level at the invasive front of EC than it is more deeply within the tumor EC." (PMID 26673619, 2016). "Target: TNF-alpha inhibitor.Mechanism of action:Increases tumor cell apoptosis:–Enhancing IL-10Induces G0-G1 cell cycle arrest:–CDK2 inhibition.T- cells activated via B7 pathway:–Tyrosine phosphorylation of CD28." (PMID 27119356, 2016). "Given the increased cell cycling of tumor cells, we reasoned that the pharmacological inhibition of CDK2 and CDK9 would increase the sensitivity of NB cells to chemotherapeutic agents." (PMID 27378523, 2016). "Data about CDK2 impact and relevance in OS, as well as information on CDKs inhibitors acitivity in this tumour, are still very scarce." (PMID 27898692, 2016). "In particular, CDK2 has proved to be deregulated in various malignancies, thus appearing as a relevant factor for the uncontrolled proliferation of tumour cells." (PMID 27898692, 2016). "The influence of SFN on Caki-1res differed from that on Caki-1par in as much as total and activated Cdk1 and Cdk2 were elevated in the everolimus-resistant tumor cells." (PMID 27863441, 2016). "Comparison of CDK2 expression between OS clinical samples and human normal osteoblasts by qRT-PCR showed a remarkable higher kinase expression in tumours compared to osteoblasts." (PMID 27898692, 2016). "In conclusion, our findings highlight the role of melatonin in the inhibition of tumor growth through the delay of G1/S through the down-regulation of CDK2 and 4 in OVCAR-429 and PA-1 cell lines." (PMID 26840297, 2016).